TRPM7 (transient receptor potential cation channel subfamily M member 7)
Diseases named in the same sentence as TRPM7 in open-access papers (continued):
Sharing a sentence is not in itself a finding about the gene and the disease.
breast carcinoma (continued). "Different cancers were linked to the expression of different calcium channels, such as TRPM7 in breast cancer and TRPM4 in prostate cancer." (PMID 35816294, 2022). "In this type of cancer, de-adhesion of cell-matrix interactions and myosin-II-based cell strains are TRPM7-dependent, and in a murine model of breast cancer, TRPM7 is required for cell metastasis into the lung." (PMID 36844925, 2022). "We then examined promoter methylation of TRPM7 using MSP approach in a cohort of breast cancers and control subjects, and found the methylation frequency of TRPM7 was 42.7% in the whole cohort." (PMID 36064388, 2022). "Previous studies have indicated that high level of TRPM7 proteins is correlated with shorter survival time in breast cancer after surgery." (PMID 36064388, 2022). "Firstly, we analyzed the expression of TRPM7 using TCGA database, and found that its expression was higher in breast cancers than that in control subjects." (PMID 36064388, 2022). "Although the molecular function of TRPM7 in breast cancer cells has been widely studied, promoter methylation of TRPM7 in breast cancers and its correlationship with clinicopathological characteristics of patients remains largely unclear." (PMID 36064388, 2022). "Considering that the regulatory effect of promoter methylation on gene expression in human cancers, we next examined promoter methylation of TRPM7 using MSP approach in a cohort of breast cancers and control subjects." (PMID 36064388, 2022). "TRPM7 can mediate breast cancer cell migration and invasion through Src and MAPK signaling pathways, without the involvement of Akt." (PMID 36158191, 2022). "More recently, it has been described that the increased expression of TRPM7 channels predicts reduced survival in patients suffering from Luminal A breast cancer." (PMID 36844925, 2022). "For these reasons, TRPM7 expression is functionally required to form metastases in mouse xenograft models and predicts poor outcome in breast cancer patients." (PMID 36158191, 2022). "Through its varied physiological roles, TRPM7 is of major importance in much human pathology in various cancers, including breast cancer." (PMID 36064388, 2022). "The TRPM7 role in breast cancer cell migration was also found in other tumors, such as ovarian cancer, and nasopharyngeal and neck squamous carcinomas." (PMID 36844925, 2022). "Despite abundant knowledge on TRPM7‐related carcinogenic pathways in human breast cancer, its role in CMT pathogenesis remains poorly understood." (PMID 33617107, 2021). "In conclusion, the data demonstrate that TRPM7 via channel activity or kinase activity is a very important player in breast cancer cell aggressivity and ability to develop metastasis." (PMID 34944940, 2021). "For example, TRP melastatin 7 (TRPM7) channels has been shown to affect the viability of breast cancer cells via modulation of the cell cycle." (PMID 33804078, 2021). "TRPM7 appears to be necessary for the proliferation and cell migration of various cancer cells including breast cancer, GC, pancreatic cancer, bladder cancer, head and neck cancer, and ovarian cancer." (PMID 34938330, 2021). "Lidocaine inhibited the proliferation and metastasis of breast cancer cells by inhibiting the function of TRPM7 channels in breast cancer cell lines." (PMID 34950031, 2021). "Most importantly, we found that TRPM7 inhibition suppresses breast cancer MCF-7 cell migration, which can be partially rescued by the overexpression of MDMX." (PMID 34627839, 2021). "The TRPM7 ion channel is a chanzyme and its kinase activity is involved in processes of tumorogenesis in breast cancer." (PMID 34944940, 2021). "This work provides a complete overview of the TRPM7 ion channel and its main involvements in breast cancer." (PMID 34944940, 2021). "Relatedly, TRPM7 is abnormally overexpressed in various cancer cells including breast cancer and knockdown of TRPM7 suppresses breast cancer cell migration and invasion." (PMID 34627839, 2021).
breast carcinoma (continued). "In the present study, we tested the role of TRPM7 as a lidocaine target for human breast cancer cells." (PMID 33435261, 2021). "We measured the effect of lidocaine on TRPM7 function, cell viability, and migration in TRPM7 expressing human breast cancer cell lines using fura-2AM-based quench, MTT, and wound-healing assays respectively." (PMID 33435261, 2021). "Recently, carvacrol was reported to affect breast cancer cells through TRPM7 mediated cell cycle regulation." (PMID 33946245, 2021). "In this review, we will present the bulk of current knowledge on the role of the TRPM7 ion channel in the initiation and progression of breast cancer, then as a potential therapeutic target." (PMID 34944940, 2021). "This supports a role for TRPM7 as a potential up-stream target of lidocaine in the viability and migration of breast cancer cells." (PMID 33435261, 2021). "Accumulating evidence has shown that TRPM7 is overexpressed in human pathologies including breast cancer." (PMID 34944940, 2021). "As the cleaved C-terminal kinase domain of TRPM7 has other activities in the nucleus, it is very likely that other mechanisms are employed by TRPM7 to promote breast cancer progression." (PMID 34627839, 2021). "In studies using human breast carcinoma cell lines, TRPM7 channels play an important role for maintaining proliferation and decreasing cell death." (PMID 34944940, 2021). "In breast cancer, the expression level of TRPM7 and the formation of metastases correlate positively, suggesting that TRPM7 contributes to a migratory and invasive phenotype." (PMID 34988012, 2021). "The roles of TRPM7 involved in breast cancer, are described in the context of the main pathophysiological processes of cancer, such as proliferation, apoptosis, EMT, migration, invasion and microcalcification." (PMID 34944940, 2021). "Chemical modulators can inhibit the activity of the TRPM7 channel more or less specifically in breast cancer cells, which can potentially be used in therapeutic applications." (PMID 34944940, 2021). "The role of TRPM7 in the lidocaine effect was confirmed in breast cancer cell line MDA-MB-231: the effect of lidocaine (0.3–1 mM) on viability and migration was reduced by the knockout of TRPM7." (PMID 33435261, 2021). "We confirmed the expression of TRPM7 in all seven breast cancer cell lines used based on expression data from open-source mRNA sequencing and proteomics data." (PMID 33435261, 2021). "The TRPM7 ion channel is suggested as a potential and prospective target in the diagnosis and treatment of breast cancer." (PMID 34944940, 2021). "This confirms the role of TRPM7 as a potential target upstream of lidocaine in the viability and migration of breast cancer cells, with a greater effect in the MDA-MB-231 cell line." (PMID 34944940, 2021). "Functional TRPM7 is observed in breast cancer cell lines (MCF-7 and hBCE cells) with a role in cell proliferation." (PMID 32887395, 2020). "Instead, mRNA evidence for TRPM7 has been reported in many breast cancer cell lines, including T47D." (PMID 31947967, 2020). "Our study contributes to the development of the TRPM7 study as a promising target against breast cancer." (PMID 31947967, 2020). "Our data provide further insight regarding the role of TRPM7 channels in the viability of breast cancer cells by the regulation of the cell cycle." (PMID 31947967, 2020). "In breast cancer cells, TRPM7 influences EMT by regulating the transcription factor SOX4 via changes in cell tension." (PMID 32825277, 2020). "Similar to HEK-M7 cells, the viability of TRPM7-expressing human breast cancer MDA-MB-231, AU565, and T47D cells were also suppressed by 2-APB by arresting the cell cycle in the S phase." (PMID 31947967, 2020). "The members of TRPM ion channel family such as TRPM2, TRPM7 and TRPM8 play vital roles in the growth, survival and metastasis of breast cancer cells, while somatic mutations affecting TRPM6 occur in breast cancer patients." (PMID 32484822, 2020).
breast carcinoma (continued). "Taken together, TRPMs most likely regulate breast cancer metastasis, though one study also indicate TRPM7 regulates breast cancer cell proliferation." (PMID 32211326, 2020). "Tumour TRPM7 mRNA expression correlates with the incidence of reoccurrence and metastasis in breast cancer patients." (PMID 32825277, 2020). "The proliferative role of TRPM7 has been demonstrated in other tumors including pancreatic adenocarcinoma, breast carcinoma, T-cell leukemia, rat basophilic leukemia, retinoblastoma, and glioblastoma." (PMID 32887395, 2020). "The evidence provided in this study helps further define the role that TRPM7 plays in breast cancer cells." (PMID 31947967, 2020). "Our results suggest that TRPM7 regulates the viability of breast cancers and is a potential therapeutic target against breast cancer." (PMID 31947967, 2020). "Xenograft models of human breast cancer revealed that increased TRPM7 expression led to increased invasiveness and metastasis." (PMID 32825277, 2020). "Further analysis show that silencing TRPM7 reduces breast cancer cells migration and metastasis by regulation of myosin II–based cellular tension and thus cell movement." (PMID 32211326, 2020). "In particular, these studies are prominent in the field of cancer; in fact, inhibition of TRPM7 expression impairs the proliferation, migration, and invasion of breast cancer cells." (PMID 32168794, 2020). "Mechanistically, the kinase domain of TRPM7 is mainly responsible for modulation of breast cancer cells migration." (PMID 32211326, 2020). "Our results suggest that TRPM7 regulates the cell cycle of breast cancers and is a potential therapeutic target." (PMID 31947967, 2020). "TRPM7 is well-studied and modulates numerous functions in breast cancer progression, especially in cancer metastasis." (PMID 32211326, 2020). "The cell line in which TRPM7 was knocked-out from MDA-MB-231 cells provided a way of determining the role of TRPM7 in a breast cancer cell line." (PMID 31947967, 2020). "In primary breast cancer tumors, higher expression of TRPM7 mRNA correlates with diminished distant metastasis free-survival and free-recurrence survival." (PMID 31275168, 2019). "In breast cancer cells, silencing TRPM7 reduced EGF-induced STAT3 activation and decreased phosphorylation levels of Src, with reduced TRPM7-mediated migration and invasion." (PMID 30995736, 2019). "Accordingly, TRPM7 knockdown induces an increase in the number of focal adhesions and contractility in the breast cancer cell line MDA-MB-231, which correlates with a reduced migratory/invasive phenotype." (PMID 31275168, 2019). "In breast cancer, myosin-II-based cell tensions and de-adhesion of cell-matrix contacts are TRPM7-dependent and TRPM7 is necessary for breast cancer metastasis into the lung in a murine model (see also below)." (PMID 29772843, 2018). "The positive correlation between the Ki67 mitosis marker and the up-regulated TRPM7 channel in breast carcinoma tissue suggests the role of this channel in breast cancer cell proliferation." (PMID 29875336, 2018). "In breast cancer, high levels of TRPM7 have been confirmed to independently predict poor outcomes and TRPM7 is functionally required for metastasis in a mouse xenograft model." (PMID 28264681, 2017). "TRPM7 is required for cell migration in breast carcinoma that involves the kinase domain of TRPM7 as well as phosphorylation of Src and MAPK." (PMID 28379203, 2017). "The proliferative role of TRPM7 has been demonstrated in a variety of malignant tumors including pancreatic adenocarcinoma, breast carcinoma, head/neck carcinoma, retinoblastoma, and glioblastoma." (PMID 28379203, 2017). "Silencing of TRPM7 in a breast cancer cell line (MDA-MB468) produced suppression of EGF-induced expression of vimentin and phosphorylation of STAT3, which are markers of EMT." (PMID 28379203, 2017).
breast carcinoma (continued). "A pro-survival role of TRPM7 channels has been demonstrated in various cancer cells, including pancreatic adenocarcinoma, gastric carcinoma, and breast carcinoma." (PMID 28379203, 2017). "Using a mouse xenograft model of human breast carcinoma, TRPM7 has been shown to be required for tumor metastasis." (PMID 28379203, 2017). "This is supported by previous work indicating the expression of both N-cadherin and vimentin proteins in breast cancer cells can be reduced by intracellular Ca2+ chelation and are partially regulated by Ca2+ channel TRPM7." (PMID 27793015, 2016). "Consistent with the association between TRPM7 and SNAI2 expression levels in our neuroblastoma cell models, we previously showed that TRPM7 activity induces cytoskeletal relaxation in breast cancer cells as well as in neuroblastoma cells." (PMID 25797249, 2015). "The expression level of TRPM7 and formation of metastases are positively correlated in breast cancer, suggesting that TRPM7 contributes to a migratory and invasive phenotype." (PMID 25852478, 2015). "High levels of TRPM7 expression predicted poor outcome in breast cancer patients and was functionally required for metastasis in a mouse xenograft model of human breast cancer." (PMID 25852478, 2015). "The specific involvement of TRPM7 has been demonstrated in the tumor cells of several cancer types, including breast cancer, gastric cancer, head and neck cancer, nasopharyngeal carcinoma, pancreatic cancer, prostate cancer, retinoblastoma and leukemia." (PMID 25965832, 2015). "This is in close agreement with our recent observations in breast cancer cells, showing that TRPM7 shRNA-mediated knockdown impairs breast cancer metastasis formation in a mouse model." (PMID 25797249, 2015). "Since intracellular ion concentrations can differ, even in the same cancer subtype, we assessed expression of the Mg2+ channel gene, TRPM7, in 49 basal subtype breast cancer tumors found in the The Cancer Genome Atlas." (PMID 25330448, 2014). "There is increasing evidence suggesting that TRPM7 plays a pivotal role in breast cancer progression and metastasis." (PMID 24952306, 2014). "In this study, a case–control study was carried out to investigate the effects of SNPs in TRPM7 genes in the development of breast cancer in Han Population of Northeast China." (PMID 24952306, 2014). "It has been demonstrated in pancreatic adenocarcinoma, breast carcinoma, and head/neck cancer, TRPM7 is aberrantly over-expressed in tissue specimens and/or cell lines." (PMID 25079291, 2014). "It has been reported that TRPM7 is abundantly expressed in a variety of human carcinoma cells, including gastric adenocarcinoma cells, lung cancer cells, and breast cancer cells." (PMID 24952306, 2014). "An accumulating amount of data shows that TRPM7 also acts as a promoter of proliferation, migration and even carcinogenesis in lung carcinoma, pancreatic carcinoma and breast cancer." (PMID 23426784, 2013). "Moreover, targeted silencing of TRPM7 in MDA-MB-435 or MDA-MB-231 breast cancer cells through gene knockout resulted in enhanced contractility and increased focal adhesions, which were closely associated with diminished migratory and invasive capabilities." (PMID 40078961, 2025). "And in a mouse breast cancer model, TRPM7 is required for cell metastasis to the lungs." (PMID 40078961, 2025). "TRPM7 silencing also inhibited the proliferation of breast cancer cell lines in vitro." (PMID 40078961, 2025). "Furthermore, recent findings highlight TRPM7 as a significant regulator of the EMT process in breast cancer." (PMID 39633507, 2024). "Furthermore, increased TRPM7 expression appears to play a key role in various characteristics of breast cancer cells, e.g., increased proliferation, altered cell adhesion, migration and invasion potential." (PMID 38255793, 2024). "TRPM7 was proposed to be a partial regulator of EMT in breast cancer cells." (PMID 38255793, 2024).
breast carcinoma (continued). "It has been suggested that the increased number of TRPM7 promotes metastasis onset while CNNM3 may influence breast cancer development by cooperating with the PRL2 oncogene." (PMID 38732186, 2024). "Our proof-of-concept experiments showed that the co-application of pharmacological inhibitors of HER2 and TRPM7 had a synergistic antiproliferative effect on HER2-positive breast cancer SKBR3 cells but not HER2-deficient MDA-MB-231 cells." (PMID 39513908, 2024). "Moreover, they have discovered that patients with breast cancer present an increased expression of membrane-bound transporters, specifically TRPM7 and CNNM3, which cooperate to maintain magnesium homeostasis." (PMID 38732186, 2024). "In summary, our data indicate that promoter methylation of TRPM7 may predict poor prognosis in patients with luminal A breast cancer." (PMID 36064388, 2022). "A recent study showed that TRPM7 was necessary for breast cancer metastasis in a mouse model." (PMID 35771152, 2022). "In addition, univariate and multivariate Cox regression showed that TRPM7 methylation served as a predictor of better survival in Lumina A breast cancer patients." (PMID 36064388, 2022). "In addition, we also observed that increased expression of TRPM7 predict poor survival in Lumina A breast cancer patients." (PMID 36064388, 2022). "Previous studies have shown that TRPM7 might be considered as a potential target for breast cancer treatment." (PMID 36064388, 2022). "In the present study, we investigated promoter methylation of TRPM7 in a cohort of breast cancers." (PMID 36064388, 2022). "Various studies support our speculation that TRPM7 plays a crucial role in the metastasis of breast cancer, and it is an independent marker of poor prognosis." (PMID 35771152, 2022). "However, epigenetic alterations (such as promoter methylation) of TRPM7 and their correlation with clinical outcomes in breast cancer patients remain largely unclear." (PMID 36064388, 2022). "Correspondingly, TRPM7 was methylated in 42.7% (93 of 219) of breast cancers." (PMID 36064388, 2022). "TRPM7 has also been recognised as independent marker of progression and metastasis if highly expressed and its silencing and inhibition were shown to suppress breast cancer cell line proliferation in-vitro, while TRPM7 knockdown reduced metastasis level in a MDA-MB-468 xenograft mouse model." (PMID 35163823, 2022). "We also found that when overexpressed, HA-TRPM7 has the capacity to bind native CNNM proteins in other cell lines (Hela, opossum kidney proximal tubule (OK), RPTEC/TERT1, and HAP1) and that endogenous TRPM7 interacts with native CNNM4 in ZR-75-1 breast cancer cells." (PMID 34928937, 2021). "Moreover, the levels of TRPM7 mRNA are significantly higher in metastatic breast cancers compared to the expression of TRPM7 in primary tumors, despite the identical number of copies of the TRPM7 gene." (PMID 34944940, 2021). "The TRPM7 gene was expressed in all of the seven human breast cancer cell lines we used." (PMID 33435261, 2021). "Multiple zinc transporters (such as ZnT2, ZIP6/LIV1, ZIP7 and ZIP10), zinc-permeable ion channels (such as TRPC6, TRPM7, and TRPV6), as well as metallothionein were reported to be overexpressed in breast cancer, some of which are associated with breast cancer metastases and poor prognosis." (PMID 34627839, 2021). "Our results showed that (a) lidocaine suppresses viability and migration of six types of breast cancer cells, but with different potency; (b) TRPM7 plays a role in mediating the effects of lidocaine on viability and migration of at least four of these breast cancer cell types." (PMID 33435261, 2021). "Calcium signals play an important role in various cancers and transport calcium ions may have altered expression in breast cancer, such as the TRPM7 calcium permeant ion channel, where overexpression may be associated with a poor prognosis." (PMID 34944940, 2021).